AXIN2 (axin 2)
Diseases named in the same sentence as AXIN2 in open-access papers (continued):
Sharing a sentence is not in itself a finding about the gene and the disease.
colorectal cancer (continued). "Importantly, SFN inhibits Wnt/β-catenin signaling in colorectal cancer cells as shown by inhibition of β-catenin-dependent luciferase reporters and repression of β-catenin target genes (AXIN2, LGR5)." (PMID 30338040, 2018). "Moreover, we demonstrated that it is sufficient to enhance the activity of AXIN2 to inhibit Wnt signaling in colorectal cancer in spite of the rather small amount of AXIN2 compared to AXIN1, which is consistent with a high importance of AXIN2 for regulating Wnt signaling in cancer cells." (PMID 39022865, 2025). "Moreover, the recent advances in molecular techniques, in particular Next-Generation Sequencing, have led to the identification of many new genes involved in the predisposition to colorectal cancers, such as RPS20, POLE, POLD1, AXIN2, NTHL1, MSH3, RNF43 and GREM1." (PMID 36768460, 2023). "Therefore, AXIN2 is frequently targeted in colorectal cancer by promoter hypermethylation." (PMID 34552611, 2021). "Moreover, these authors showed the expression of AXIN2 in developing mouse teeth and suggested that genes involved in colorectal cancer could also be involved in tooth development." (PMID 29445242, 2018). "Different studies have pinpointed the parallelisms between mouse and human colorectal cancer at epigenetic level and many of the genes we have found hypermethylated in early stages of mouse tumorigenesis (i.e., Lgr5, Axin2 and En1) may have potential clinical applications in human cancer." (PMID 25933092, 2015). "Specifically, in colorectal cancer, ALKBH5 exhibits an immunosuppressive activity by targeting AXIN2." (PMID 40746892, 2025). "Aberrant methylation of Adenomatous Polyposis Coli (APC), Dickkopf (DKK), axis inhibition protein 2 (AXIN2), and secreted frizzled-related protein (SFRP) has been identified in colorectal cancer." (PMID 36765652, 2023). "Activation of the Wnt/β-catenin signaling pathway drives colorectal cancer growth by deregulating the expression of many downstream targets, such as c-JUN, c-Myc, cyclin D1, CD44 and Axin2." (PMID 35065674, 2022). "LINC01315 was also found to be correlated with DPEP1, KRT23, ASCL2, AXIN2, and DUSP4 in colorectal cancer." (PMID 35470736, 2022). "The Western blot results show that compounds 15o and 15r inhibited the expression levels of PI3K p85, β-actin, AXIN-2, TAB-182, and β-catenin proteins, as these markers are involved via the β-catenin pathway in colorectal cancer." (PMID 36364474, 2022). "This compound inhibited the expression of various Wnt target genes (such as MYC, AXIN2, and CD44) through conformational modification of TNIK and abrogated the stemness of colorectal cancer cells." (PMID 32429395, 2020). "Further western blotting results showed that the endogenous Wnt responder gene expression of cyclin D1, c-Myc, and Axin2 was suppressed in HT29, HCT116, and SW480 colorectal cancer cells treated with 4βHWE." (PMID 30909473, 2019). "We hence analyzed SW480 colorectal cancer cells and observed that transiently expressed MYC2-TNKS2 and endogenous AXIN2 accumulate in puncta upon XAV939 treatment." (PMID 27494558, 2016). "The differential expression of the genes AXIN2 and CCND1 in the three colorectal cancer cell lines highlights the fact that the genetic background of a given cell has a major impact on the expression of a specific gene." (PMID 24467841, 2014). "We then investigated the effects of PKN1 and PKN2 siRNAs on WNT3A-dependent AXIN2 expression in osteosarcoma (U2OS), and colorectal carcinoma (RKO) cell lines." (PMID 24114839, 2013). "In the present study, we noted that TNKS inhibition through the broadly used TNKS inhibitor G007‐LK failed to inhibit Wnt/β‐catenin signaling in AXIN2 knockout colorectal cancer cells." (PMID 39022865, 2025). "Additionally, the POP112 line did not harbour mutations or deep amplifications or deletions in the WNT pathway members defined as colorectal cancer drivers APC, AXIN1, AXIN2, CTNNB1, GSK3B or RNF43, and only a shallow deletion in ZNRF3." (PMID 38324534, 2024).
colorectal cancer (continued). "In fact, AXIN2 is not the only Wnt negative regulator known to be silenced by promoter hypermethylation in colorectal cancer: hypermethylation has been detected in negative regulators including WIF1, SFRP1/2/4, DKK1–3 and NOTUM." (PMID 33202731, 2020). "Previously, epigenetic silencing of Axin2 was reported in colorectal carcinoma with microsatellite instability (MSI+ CRC), and forced expression of Axin2 results in rapid cell death in an MSI+ CRC cell line, indicating a role of epigenetic silencing of Axin2 in carcinogenesis of MSI+ CRC." (PMID 24474204, 2014). "Also, caperatic acid tended to reduce Axin2 expression in both colorectal cancer cell lines, although the changes were not statistically significant." (PMID 28887754, 2018). "However, we found that knockdown of TGIF1 has no obvious effects on β-catenin and Axin2 protein levels in the nuclei of colorectal cancer cells." (PMID 29050273, 2017). "It has been recently demonstrated that CDX2 regulates gene expression of APC and AXIN2, components of the β-catenin degradation complex, and increasing evidences indicate that CDX2 inhibits the activity of β-catenin and thereby the progression of the colorectal cancer." (PMID 26910375, 2016). "Moreover, the high AXIN2 dependency of Wnt pathway inhibition by TNKS inhibitors in colorectal cancer cells implies that TNKS inhibitors will never block Wnt signaling completely because this would prevent transcription of the β‐catenin target gene AXIN2, causing AXIN2 depletion." (PMID 39022865, 2025). "Our findings support a tumor suppressor role for SALL2 in colorectal cancer, mediated in part through a previously unrecognized SALL2-dependent regulatory mechanism involving AXIN2, a key negative modulator of Wnt/β-catenin signaling." (PMID 40869218, 2025). "However, the expression level overcompensating increase of AXIN1 failed to rescue the decrease of AXIN2 functionally because knockout or knockdown of AXIN2 activated Wnt signaling, suggesting that AXIN2 is crucial for Wnt pathway regulation in colorectal cancer cells." (PMID 39022865, 2025).
colon carcinoma (64 papers, 2009 to 2025). "Corroborating this finding, we found that PrPC silencing in MDST8 or SW480 colon cancer cells reduced the levels of AXIN2 mRNA, while its overexpression in LoVo cells was associated to an opposite increase in AXIN2 transcripts." (PMID 38589873, 2024). "It is important to document as many cases of Axin2 mutations as possible to better understand a patient’s future risk of developing colon cancer; this will help to create guidelines and direct management for future physicians." (PMID 34858573, 2021). "This highlights the importance of a thorough review of system when screening for colon cancer as well as documenting cases of Axin2 mutations to create management guidelines for these patients." (PMID 34858573, 2021). "KIAA1211 overexpression in human colon cancer cell lines was shown to downregulate Wnt/β-catenin target genes (including the SHF-associated AXIN2) and can positively regulate the actin polymerization in vitro in adult intestinal tissue extracts." (PMID 31234534, 2019). "As a TCF/LEF target gene, the Axin2 is highly expressed in colon cancer due to loss of APC tumor suppressor function or β-catenin mutation, and we validated increased Axin2 abundance in colon cancer cell panels." (PMID 28418862, 2017). "Of note, a subgroup of colon tumors derived from Pygo2 deficient animals showed significant repression of Axin2, suggesting that Wnt/ß-catenin signaling is partially inhibited in these tumors of Pygo2 deficient mice." (PMID 27811361, 2016). "The AXIN2 P50S variant is unlikely related to the familial tooth agenesis or the colon cancer phenotype in this family." (PMID 24607150, 2014). "We also assayed for the presence of AXIN2 mutations in the only two probands presenting with colon cancer and tooth agenesis, and in family members with tooth agenesis but not cancer." (PMID 24607150, 2014). "AXIN2 encoding a Wnt signaling component and promotes colon carcinoma oncogenic activity." (PMID 33552955, 2020). "Patients with Axin2 germ-line mutations display a predisposition to colon cancer development." (PMID 29652830, 2018). "Indeed, in our study, AXIN2 was frequently hypomethylated in MSS cancers, suggesting that the epigenetic change of AXIN2 specifically associates with the MSI pathway for colon cancer." (PMID 24964857, 2014). "For instance, frameshift mutations of AXIN2 in MSI colon cancers may be one such additional mechanism." (PMID 24964857, 2014). "Although phosphorylation of β‐catenin is blocked via multiple mechanisms in colon cancer, such as APC truncation and AXIN2 mutation, we found that CRC cell lines, such as MC38, CT26, and Caco‐2 cells exhibit phosphorylated β‐catenin." (PMID 40884233, 2025). "Research has found abnormally expressed AXIN2 in cancers such as hepatocellular-cholangiocarcinoma, colon cancer and lung cancer." (PMID 40963862, 2025). "Accumulated evidence suggests that AXIN2 has close relations with the development of colon cancer, breast cancer, liver cancer and so on." (PMID 37074454, 2023). "Another study suggested that the transactivation of AXIN2 inhibited colon cancer cell proliferation and tumor formation by inhibiting Wnt/β-catenin signaling." (PMID 35484177, 2022). "Collectively, these results indicate that Zic2 exerts multilevel regulation on Wnt signaling through interaction with β-catenin and repression of Axin2 in colon cancer." (PMID 34099631, 2021). "Taken together, these results led us to conclude that Zic2 promotes colon cancer growth by activating Wnt signaling via interaction with β-catenin and repression of Axin2." (PMID 34099631, 2021). "Collectively, in addition to directly repressing Axin2 transcription, Zic2 also interacts with β-catenin to activate Wnt signaling in colon cancer." (PMID 34099631, 2021). "The inverse correlation between Zic2 and Axin2 was further validated by IHC analysis of human colon cancer samples." (PMID 34099631, 2021).
colon carcinoma (continued). "Zic2 functions in colon cancer, at least in part, by enhancing Wnt/β-catenin signaling via collaboration with β-catenin and repressing Axin2." (PMID 34099631, 2021). "CDX2 transactivates the expression of GSK-3β and Axin2 to inhibit the cell proliferation and tumor formation in colon cancer." (PMID 31200542, 2019). "Tumour-suppressor genes (MLH1 and RUBCNL), protooncogene (AGR2), and genes reported to be linked with colon cancer (EPDR1, MLH1, AXIN2) were enriched in the signature." (PMID 31008109, 2019). "It is important to note that in rare cases of colon cancers, the wild-type of the APC, Axin1 or Axin2 gene is mutated." (PMID 29652830, 2018). "Consistently, qPCR analysis revealed that the expression of genes associated with colon cancer stem cells, including CD44, CD133, LGR5, and AXIN2, was reduced in SREBP1 and SREBP2 knockdown DLD1 and Pt130 cells." (PMID 29449559, 2018). "Chr7:27225772 at the HOXA11 promoter and chr17:63554340 at the AXIN2 promoter were also detected as colon cancer-specific cDMCs." (PMID 28751909, 2017). "Axin2, a representative downstream target of TCF/LEF transcriptional machinery, is highly abundant in colon cancer cells as well as in adenomas due to loss of APC function." (PMID 28418862, 2017). "Conversely, when Axin and Snail levels were increased with tankyrase inhibitor XAV939, cell migratory potential significantly increased, supporting that Axin2 serves tumor progression in colon cancer cells." (PMID 28418862, 2017). "A similar polarization of methylation states among the colon cancer cell lines was observed at the AXIN2 cDMC." (PMID 28751909, 2017). "Whereas there were small context-dependent differences, the canonical and bona fide colon cancer WNT-TCF targets AXIN2 and LGR5 were generally repressed at 5μM CAP2 (batch 2)." (PMID 27973612, 2016). "The levels of expression of the bona fide colon cancer WNT-TCF activity biomarker AXIN2, as well as the WNT-regulated stem cell markers LGR5 and ASCL2, were determined by RT-qPCR in transduced cells in vitro and in subcutaneous xenografts." (PMID 26939070, 2016). "Analyses in three colon cancer cell types revealed the epistatic rescue of the expression of AXIN2 from CAP2 repression in cells with TCFVP16." (PMID 27973612, 2016). "In fact, gene therapies delivering DKK3 and AXIN2, which were demonstrated to be targets of miR-582-3p in this study, are being clinically tested in prostate cancer and colon cancer, respectively (NCT01197209, NCT01882660)." (PMID 26468775, 2015). "In the present study, we sequenced the AXIN2 gene locus in two probands presenting colon cancer and tooth agenesis (although the milder form, hypodontia) and having relatives with tooth agenesis." (PMID 24607150, 2014). "In contrast with the epigenetic silencing of AXIN2 in MSI colon cancer, up-regulation of AXIN2 mRNA was reported in MSS cancers." (PMID 24964857, 2014). "Mutations of β-catenin, Axin2 and GSK-3β that lead to hyperactive Wnt signaling are also found in colon cancers." (PMID 24955294, 2014). "A further study found that maoecrystal I decreased the expression of Wnt signaling target genes, including c-myc, cyclin D1, survivin and Axin2 in colon cancer cells." (PMID 24955294, 2014). "PGC using expO data revealed that breast, prostate and colon tumors had a strong association between FOXQ1 and Wnt related genes (t values>3 for AXIN2 and APCCD1)." (PMID 23555880, 2013). "Stabilizing Axin2 and activation of CK1α also were taken as effective mechanisms to inhibit Wnt signaling for targeted therapeutics against colon cancer." (PMID 23844215, 2013). "Moreover, employing the SurvExpress platform, we found evidence that colon cancer patients with higher cancer risk exhibited lower levels of SALL2 and AXIN2 compared to those with lower cancer risk." (PMID 40869218, 2025).
colon carcinoma (continued). "Wnt activates β-catenin and induces the formation of a complex with SP1 that binds the promoter of the Axin2 gene to activate the transcription in colon cancer, and Axin2 expression is quickly suppressed following dephosphorylation of LRP6 in the lipid raft by a porcupine inhibitor." (PMID 33430034, 2021). "All of these results indicate that Zic2 could bind to specific areas of the Axin2 promoter and transcriptionally activate Axin2 in colon cancer cells." (PMID 34099631, 2021). "Furthermore, our study demonstrated that CDX2 specifically and directly binds to the GSK-3β promoter and the Axin2 upstream enhancer in colon cancer cells, by qChIP." (PMID 30631044, 2019). "Further, canonical Wnt transcriptional activity, Axin2 transcript abundance, and E-cadherin reporter activity were minimally changed by niclosamide treatment in Axin2 knockdown colon cancer cells, indicating that Axin2 is required for mode of action (MoA) of niclosamide on colon cancer cells." (PMID 28418862, 2017). "Epigenetic silencing of AXIN2 in MSI colon cancer was reported in 2006." (PMID 24964857, 2014). "However, silencing AXIN2 decreases the invasive and metastatic characteristics of colon cancer." (PMID 35550582, 2022). "In fact, genes such as Axin2 and miR-195-5p are multi-target in colon cancer, and the overexpression/manipulation of them may affect the expression of other genes, thus resulting in the expression of beta-catenin inconsistent with the common regulatory relationship." (PMID 34706645, 2021). "Strikingly, most of the Wnt genes upregulated by HMGA1 in our murine model are also upregulated in human colon cancer, including the WNT effectors, ASCL2, AXIN2, CTNNB1, MYC, EPHB2, CD44, and ETS2 and the WNT receptors, LGR5, LRP5, and LRP6." (PMID 39895630, 2025). "ZIC2 can transcriptional regulates Src, lncRNA SNHG12, Axin2, Runx2, OCT4, STAT3, PAK4 expression in non-small cell lung cancer, endometrial cancer, colon cancer, ccRCC, lung adenocarcinoma, liver cancer, and breast cancer 15, 28, 36-41." (PMID 37496990, 2023). "A translational clinical study was conducted, investigating the effect of pre-operative decitabine on the methylation and expression of WNT target genes APCDD1, AXIN2 and DKK1 and global methylation in colon cancer patients." (PMID 34068407, 2021). "Previously, we have shown that methylation of the WNT target genes APCDD1, AXIN2 and DKK1 predicts poor prognosis in stage II colon cancer patients." (PMID 34068407, 2021). "IRG signature of AXIN2, CCL22, CLEC10A, CRIP2, RUNX3, and TRPM5 is a reliable prognostic predictor for colon cancer patients." (PMID 33401247, 2020). "Taken together, our observations support the positive correlation between CDX2 and SI as well as the negative regulatory action of CDX2 on the designated Wnt targets AXIN2, cMYC, and CYCLIND1 in colon cancer cells." (PMID 32814764, 2020). "AXIN2 was silenced in MSI subgroup, possibly as a result of methylation of its promoter region frequently observed in MSI colon cancer patients." (PMID 31008109, 2019). "Over-expression of NKD1 and AXIN2 correlates with the activated WNT/β-catenin pathway in cell lines and in the human colon tumor." (PMID 31434359, 2019). "Silencing of Axin2 expression in colon cancer cells inhibits EMT and inhibit the metastatic and invasive properties of colon cancer cells." (PMID 29652830, 2018). "In another study it was shown that Axin2, a canonical Wnt suppressor, promotes EMT in colon cancer cells." (PMID 29652830, 2018).